ICAM1 (intercellular adhesion molecule 1)
Diseases named in the same sentence as ICAM1 in open-access papers (continued):
Sharing a sentence is not in itself a finding about the gene and the disease.
glioblastoma (33 papers, 1994 to 2026). The most malignant astrocytic tumor (WHO grade IV). "ICAM-1's production was enhanced in glioblastoma through the incubation of TAMs (tumor associated macrophages) in a hypoxic conditions with the addition of a HIF (hypoxia-inducible factor)-stabilizing drug." (PMID 39050471, 2024). "Radiation can further increase the interaction of the nuclear STAT3/ NFκB p65 complex with the proximal intron-1 region of the ICAM-1 gene in glioblastoma multiforme." (PMID 37821959, 2023). "CD11a and CD49d have been implicated in T-cell glioblastoma-infiltration in a previous study in vitro, where transmigration of T-cells across glioblastoma-isolated ECs occurred in a ICAM-1 and VCAM-1-dependent manner." (PMID 35464424, 2022). "We also identified expression of ICAM-1 and VCAM-1, the cognate receptors for the CD11a and CD49d integrins respectively, at the gene level within glioblastoma-associated clusters via scRNA-seq." (PMID 35464424, 2022). "Research suggests that ICAM-1 is potentially an important mediator of tumor migration and invasion in chemotherapy resistant glioblastoma." (PMID 34207434, 2021). "Targeting ICAM-1 offers potential for overcoming glioblastoma’s resistance to antiangiogenic therapy and improve prognosis." (PMID 34207434, 2021). "Moreover, pericytes associated with glioblastoma multiforme (GBM) fatal brain tumors, contribute to the immune-suppressive micro-environment of this cancer by reduced expression of ICAM1 in response to pro-inflammatory cytokine IL-1β." (PMID 34408980, 2021). "Combined ICAM-1/VCAM-1 blockade showed the strongest impairment of T cell infiltration in glioblastoma." (PMID 33262763, 2020). "We found that the expression of intercellular adhesion molecule-1 (ICAM-1, also known as CD54) in glioblastoma tumors from bevacizumab-treated mice was higher than that in the glioblastoma tumors from vehicle-treated control mice." (PMID 29228586, 2017). "Our findings suggest that ICAM-1 is a potentially important mediator of tumor migration and invasion in bevacizumab-resistant glioblastoma." (PMID 29228586, 2017). "Intercellular cell adhesion molecule 1 (ICAM-1; also known as CD54) is overexpressed in bevacizumab-resistant glioblastoma." (PMID 29228586, 2017). "A recent report indicated that Notch1 stimulation of glioblastoma stem cells resulted in the enhanced expression of ICAM-1." (PMID 26218064, 2015). "Indeed, we identified expression of ICAM-1 and VCAM-1 at the gene level within glioblastoma-associated clusters via scRNA-seq." (PMID 35464424, 2022). "In addition, in glioblastoma increased infiltration of CD8+ T cells also correlated with the expression of ICAM-1 and VCAM-1 on the vessel surface Either, ICAM-1 and VCAM-1 blocking antibodies reduced T cell infiltration." (PMID 33262763, 2020). "In the present study, we tested our hypothesis that highly expressed ICAM-1 mediates glioblastoma’s resistance to antiangiogenic therapy." (PMID 29228586, 2017). "We hypothesized that highly expressed ICAM-1 partly mediates glioblastoma’s resistance to antiangiogenic therapy." (PMID 29228586, 2017). "Targeting ICAM-1 may provide a new strategy for enhancing the efficacy of antiangiogenic therapy against glioblastoma and preventing the invasive phenotype of the disease." (PMID 29228586, 2017). "Together, these results suggest that targeting ICAM-1 could be a useful approach in overcoming glioblastoma’s resistance to antiangiogenic therapy, thereby improving the prognosis of patients with this disease." (PMID 29228586, 2017). "Our groups and others have shown that all trans retinoic acid (ATRA) can modify the immunogenicity of tumor cells both in vitro and in vivo through differential regulation of MHC class I and intercellular adhesion molecule-1 (ICAM-1) as well as increase the sensitivity of glioblastoma to NK-cells." (PMID 25346943, 2014).
glioblastoma (continued). "Indeed, when coculturing glioblastoma spheroids together with vessel-forming HUVECs in the cancer-on-a-chip, the vessels showed increased ICAM-1 expression in the presence of both LV-Ctrl and LV-TF spheroids, whereas VE-cadherin expression was only increased in the U251 LV-TF condition." (PMID 39268353, 2024). "In human glioblastomas, PAK4 reduces the expression of intercellular adhesion molecule 1 (ICAM-1) and vascular cell adhesion molecule 1 (VCAM-1) via SLUG, thereby diminishing T cell adhesion to tumor endothelial cells." (PMID 40332759, 2025). "We found high expression of ICAM1 and high expression of MMP9 was related to shorter survival in glioblastoma multiforme patients." (PMID 37732732, 2023). "To investigate the role of these accessory adhesion receptor interactions in target cell recognition, we utilized the HLA-A*02:01+ U87 glioblastoma cell line, which expresses CD58 and ICAM-1." (PMID 36598945, 2023). "In glioblastoma, increased MSN expression increased the expression of β-catenin, CD44, ICAM-1, and MMP-2.28." (PMID 37446127, 2023). "Together, these data suggest that CD11a-ICAM-1, CD49a and CD49d-VCAM-1 contribute to the infiltration of subsets of T cells into glioblastoma." (PMID 35464424, 2022). "Importantly, it had been reported that expressional levels of ICAM1 serve as a predictor of clinical outcome in several types of cancer including metastatic colorectal cancer, indolent non-Hodgkin lymphomas, high-grade serous ovarian carcinoma and glioblastoma." (PMID 34408980, 2021). "ICAM-1, also known as CD54, was reported to be overexpressed in bevacizumab-resistant glioblastomas in a mouse xenograft model." (PMID 29670046, 2018). "NFκB induces expression of adhesion molecules, including ICAM-1, VCAM-1, and selectins, and NFκB-dependent induction of VCAM-1 was recently reported to promote glioblastoma cell adhesion and invasion." (PMID 24466111, 2014). "Recent study about molecular mechanisms of the cell migration in glioblastoma indicated that MSI1 promotes cell migration by inhibition in translation of Tensin3, a negative regulator of migration, and overexpression of Intercellular Adhesion Molecule-1 (ICAM1)." (PMID 32448364, 2020). "After miR‐218 overexpression in glioblastoma cells, we observed a decrease in the expression levels of GBM oncogenes such as PIK3CA, ROCK1, LAMC1 and ICAM1." (PMID 35702951, 2022).
leukemia (31 papers, 2008 to 2025). A malignant (clonal) hematologic disorder, involving hematopoietic stem cells and characterized by the presence of primitive or atypical myeloid or lymphoid cells in the bone marrow and the blood. "Further, some cancers, such as cholangiocarcinoma and leukemia, have only one point mutation in ICAM1." (PMID 37671167, 2023). "ICAM-1 and ITGB2 are documented as ligand-receptor, and previous studies have shown that ICAM-1 is highly expressed on the surface of leukemia cells." (PMID 38971796, 2024). "In AML, STAT3 from the nuclear extract of patient leukemia cells stimulated with IL-6 binds the probe of an IL-6 responsive element derived from the ICAM1 promoter." (PMID 39034990, 2024). "Intercellular adhesion molecule-1 (ICAM-1) peptide sequence derived from cell surface proteins can be specifically endocytosed by leukemia T-cells." (PMID 38399294, 2024). "Upon treatment with exosomes derived from leukemia cells, endothelial cells show increased expression of vascular cell adhesion molecule 1 (VCAM-1) and intercellular adhesion molecule 1 (ICAM-1), which have been associated with neovascularization." (PMID 37895415, 2023). "NALM-6 leukemia cells were then cultured with the endothelial monolayer to determine if their adhesive abilities were mediated by raised ICAM-1 and VCAM-1 expression in SPINK1-treated HUVECs." (PMID 35194087, 2022). "The expression of VCAM1, VEGFA, PECAM1, and ICAM1, which promote leukemia cells to cross the BBB, was studied by RT-PCR." (PMID 35256780, 2022). "Since IFNγ promotes ICAM-1 expression on leukemia cells, HPC-NK cells were co-cultured overnight with K562 or THP-1 with or without N-803, whereupon ICAM-1 expression was analyzed." (PMID 33140189, 2021). "We found that ICAM-1 was highly expressed in mouse and human leukemia cell lines, but was low expressed in HSCs in bone marrow, indicating that the adhesion molecules on the surface of nanoparticles are important reasons in mediating the specific targeting of leukemic cells." (PMID 38971796, 2024). "Mesenchymal stem cells in the BM TME may also support T-ALL by accepting damaged mitochondria from leukemia cells through ICAM-1:integrin-mediated cell adhesion." (PMID 39482533, 2024). "Moreover, the biomimetic vesicles exhibit superior binding affinity to leukemia cells through intercellular cell adhesion molecule-1 (ICAM-1)/integrin β2 (ITGB2) interaction." (PMID 38971796, 2024). "In addition, N-803 increases ICAM-1 expression on leukemia cells after HPC-NK cell co-culture and improves (serial) leukemia killing." (PMID 33140189, 2021). "Exosomes derived from K562 leukemia cells (LEXK562) are membrane-bound vesicles with diameters of approximately 50–100 μm and harbor adhesion molecules (e.g., intercellular adhesion molecule-1) and immunologically associated molecules (e.g., heat shock protein 70)." (PMID 24622345, 2014). "Research has shown that the hypomethylation agent (HMA) decitabine can upregulate the level of ICAM-1(CD54) and CD48 on AML cells, thereby activating NKs to kill leukemia cells while reversing immune evasion by leukemia cells." (PMID 40008144, 2025). "ITGB2 is a classical adhesion ligand, and its receptor is ICAM-1 (CD54), which is highly expressed in leukemia cells." (PMID 38971796, 2024). "Notably, both ICAM-1 and VCAM-1 protein levels were elevated in tumor-associated myeloid subsets relative to those in healthy littermate controls, which could contribute to the superior leukemia-supportive capabilities of tumor-associated myeloid cells." (PMID 37805579, 2023). "We examined the expression of VCAM-1 and ICAM-1 in the marrow vascular niche of normal and ICN1 leukemia mice." (PMID 35401837, 2022). "We found that VCAM-1 and ICAM-1 were expressed in normal bone marrow ECs, but mice engrafted with ICN1 leukemia exhibited increased expression of both adhesion molecules." (PMID 35401837, 2022).
leukemia (continued). "The cytotoxicity of cytotoxic T lymphocytes was increased by exposure to leukemia-derived EVs that contained high levels of HSP70 and ICAM1, thereby enhancing leukemia antigen presentation." (PMID 36106632, 2022). "Collectively, these data show that N-803 boosts IFNγ production by HPC-NK cells, promotes ICAM-1 expression on leukemia cells and improves HPC-NK cell-mediated leukemia killing." (PMID 33140189, 2021). "OP9/L cells showed significant down-regulation of Cdkn genes and up-regulation of Icam1, leading to the increased proliferation capacity of OP9 cells and enhanced transmigration of leukemia cells through them." (PMID 26218064, 2015). "The RT-PCR results confirmed the greater expression of CCL2, ICAM1, IL8 and IL1B in BMSCs co-cultured with leukemia cells compared with BMSC mono-cultures." (PMID 24304929, 2013). "Inhibiting ICAM-1 and VCAM-1, which respectively bind the integrins LFA-1 and VLA-4 that are expressed by T-ALL cells, or inhibiting FAK/PYK2 signaling reduced leukemia burden across multiple organs, including the spleen and liver, and prolonged mouse survival." (PMID 39482533, 2024). "To investigate if the adhesion between leukemia cells and ECs induces EC UPR response and PERK activation, we blocked the ligands of ICAM-1 and VCAM-1 and found that PERK, eIF2a, and JAG1 activation was modestly attenuated by blocking LFA-1 but largely unaffected by blocking VLA-4." (PMID 35401837, 2022). "On leukemia cells, co-culture with HPC-NK cells and N-803 increased ICAM-1 expression." (PMID 33140189, 2021). "We found that luteolin decreased the levels of interleukin- (IL-) 6, IL-8, soluble intercellular adhesion molecule-1 (sICAM-1), and monocyte chemoattractant protein-1 (MCP-1) and attenuated adherence of the human monocytic leukemia cell line THP-1 to IL-1β-stimulated ARPE-19 cells." (PMID 33122970, 2020).
autoimmune disease (29 papers, 2009 to 2025). A disorder resulting from loss of function or tissue destruction of an organ or multiple organs, arising from humoral or cellular immune responses of the individual to their own tissue constituents. "ICAM-1 has also been implicated in the pathophysiology of diverse diseases from cardiovascular diseases to autoimmune disorders, certain infections, and cancer." (PMID 37237555, 2023). "Human ICAM-1 mediates adhesion and migration of leucocytes, and is implicated in inflammatory pathologies, autoimmune diseases and in many cancer processes." (PMID 23936131, 2013). "Polymorphisms of ICAM-1 K469E and G241R are common genetic variation in populations and associated with several autoimmune diseases, such as multiple sclerosis, type 1 diabetes, or Crohn's disease." (PMID 19822019, 2009). "Research has also demonstrated that polymorphisms in the ICAM-1 and VCAM1 genes are associated with an increased genetic risk for various autoimmune diseases." (PMID 39409189, 2024). "Furthermore, our results showed that microbiota composition was associated with ICAM-1, the expression of which contributes to the clinical manifestations of a variety of diseases, predominantly by interfering with normal immune function in oncology, cardiovascular, and autoimmune diseases." (PMID 37110459, 2023). "Correlations were observed between elevated levels of ICAM-1 and the progression and severity of cancer, cardiovascular disease, and autoimmune disorders." (PMID 34206599, 2021). "CD54 is a ligand for lymphocyte function-associated antigen-1, also known as intracellular adhesion molecule-1 (ICAM-1), is involved in T cell-induced autoimmune disease." (PMID 31867004, 2019). "Other cell-surface molecules like ICAM-1 and HLA-DR have been shown to be involved in the initiation and propagation of autoimmune diseases." (PMID 28946890, 2017). "Given the importance of ICAM-1 antagonism in different autoimmune diseases, Eap is believed to be the most potent factor for inhibition of T-cell migration into the CNS." (PMID 25644616, 2015). "We report here an association of increased expression of ICAM-1 on monocytes with a less favorable response to TNF inhibition, which would imply them in the perpetuation of the autoimmune disease." (PMID 26251236, 2015). "Based on these roles in several disease pathologies, the LFA-1/ICAM-1 interaction can serve as a potential therapeutic target in the development of new therapies for the autoimmune diseases, metastasis cancer, and viral diseases." (PMID 25032811, 2014). "While implicated variants were largely trait-specific, 40% of target genes of these variants (2,207 of 5,488) were implicated across more than one autoimmune disorder, with 11 genes implicated across a maximum of 9 traits (e.g., TYK2, ICAM1, ICAM3, TNFIP3, CLEC16A, BACH2)." (PMID 41361473, 2025). "Autoimmune diseases in G6PD deficient patients may be triggered by activation of TGF-β/NADPH oxidases/ROS signaling, the expression of ICAM-1 and VCAM-1, and the adhesion of leukocytes to the endothelial cells with endothelial to mesenchymal transition." (PMID 37753082, 2023). "However, in autoimmune diseases and certain types of infection, ICAM-1 can be involved in directing cells to damage healthy tissue." (PMID 37237555, 2023). "VCAM-1 and ICAM-1 are two important cell adhesion molecules, which participate in the adhesion and migration of immune cells and play an important role in the pathological process of inflammation, tumor metastasis, and autoimmune diseases." (PMID 35674582, 2022). "It is widely involved in infectious diseases, autoimmune diseases and tumors via upregulating intercellular adhesion molecule-1 (ICAM-1), mediating the infiltration of inflammatory cells and T lymphocytes, and producing antibodies with the synergistic assistance of cytokines." (PMID 35665407, 2022).
autoimmune disease (continued). "Overall, the signal transduction mediated by LFA-1 and ICAM-1 is involved in the migration, cell adhesion, and activation processes of lymphocytes, as well as the formation of immune synapses, which makes LFA-1 and ICAM-1 closely associated with infection and autoimmune diseases." (PMID 36206304, 2022). "However, the irregular expressions of LFA-1 or ICAM-1 or both have also been related to the specific pathologies of several autoimmune diseases such as multiple sclerosis (MS), leukocyte adhesion deficiency (LAD), thyroiditis, and insulin-dependent diabetes mellitus (IDDM)." (PMID 25032811, 2014). "IL1RL2, IL6R, ERBB3, ICAM1, IL1R1, and GALK1 were also enriched in categories like immune system disease, autoimmune disease, skin disease, and disease of anatomical entity." (PMID 38773393, 2024). "Targeting the interaction between ICAM-1 and LFA-1 as a treatment for (auto)immunity has been the subject in a number of studies, and was shown to have beneficial effects in animal models for autoimmune diseases." (PMID 21589878, 2011). "In addition, the removal of palindromic SNPs and adjustment for confounding traits, such as soluble intercellular adhesion molecule 1, C‐reactive protein level, and autoimmune diseases, also did not influence the findings." (PMID 38313187, 2024). "The blockade of ICAM-1 interactions with its ligand LFA-1, is a potential target for immunosuppression in our system, and its relevance as adhesion-based therapeutic strategy has been shown in various inflammatory conditions such as in autoimmune diseases and organ transplantation." (PMID 32907600, 2020).